RNU5A-8P (RNA, U5A small nuclear 8, pseudogene)
Gene: Small nuclear RNA gene on chromosome 1 (210,374,154 to 210,374,267, reverse strand). Ensembl gene ENSG00000200972.
Homologues: Orthologues: chimpanzee U5 (80% identical), zebrafish U5 (59% identical). Paralogues in human: RNU5E-4P (74% identical), RNU5F-7P (72% identical), RNU5F-6P (71% identical), RNU5A-6P (69% identical), RNU5E-6P (69% identical), RNU5A-3P (68% identical), RNU5B-2P (68% identical), RNU5B-4P (68% identical), RNU5E-5P (68% identical), RNU5A-4P (68% identical), RNU5E-7P (68% identical), RNU5F-4P (68% identical), and 13 more.